GNAL (G protein subunit alpha L)
Description:
Guanine nucleotide-binding protein (G protein) involved as transducer in olfactory signal transduction controlled by G protein-coupled receptors (GPCRs) (By similarity). Contains the guanine nucleotide binding site and alternates between an active, GTP-bound state and an inactive, GDP-bound state (By similarity). Signaling by an activated GPCR promotes GDP release and GTP binding (By similarity). The alpha subunit has a low GTPase activity that converts bound GTP to GDP, thereby terminating the signal (By similarity). Both GDP release and GTP hydrolysis are modulated by numerous regulatory proteins (By similarity). GNAL/G(olf) alpha specifically mediates olfactory signal transduction within the olfactory neuroepithelium and the basal ganglia following GPCRs activation (By similarity). Acts by promoting the specific activation of adenylyl cyclase ADCY3, resulting in increased levels of the signaling molecule cAMP (By similarity).
Synonyms: DYT25; HG1O
Tractability: Small molecule: a structure with a bound ligand is known. Antibody: its Gene Ontology location is reachable by antibodies, with high confidence; UniProt places it where antibodies can reach, with medium confidence. PROTAC: ubiquitination databases record sites on it; its protein half-life has been measured.
Gene: Protein-coding gene on chromosome 18 (11,689,264 to 11,885,685, forward strand). Ensembl gene ENSG00000141404.
Subcellular location: Cell membrane
Subcellular location (Human Protein Atlas): Cytosol; Plasma membrane
Pathways (Reactome):
Neuronal System: Adenylate cyclase inhibitory pathway
Sensory Perception: Olfactory Signaling Pathway
Signal Transduction: Adenylate cyclase activating pathway
Gene Ontology:
Molecular function: protein binding; G protein activity; G protein-coupled receptor binding; G-protein beta/gamma-subunit complex binding; GTPase activity; GTP binding; guanyl nucleotide binding
Biological process: adenylate cyclase-activating dopamine receptor signaling pathway; adenylate cyclase-activating G protein-coupled receptor signaling pathway; sensory perception of chemical stimulus; sensory perception of smell; signal transduction; G protein-coupled receptor signaling pathway
Cellular component: extracellular exosome; cytoplasmic side of plasma membrane; plasma membrane
Genetic constraint (gnomAD): Loss-of-function variants: 9 observed, 8.73 expected, observed/expected ratio (o/e) 1.03, 90% interval 0.62 to 1.72. That is too few expected variants to judge how well the gene tolerates losing a copy. Missense variants: 269 observed, 210.02 expected, observed/expected ratio (o/e) 1.28, 90% interval 1.16 to 1.42. Synonymous variants: 140 observed, 90.52 expected, observed/expected ratio (o/e) 1.55, 90% interval 1.35 to 1.78.
Homologues: Orthologues: chimpanzee GNAL (99% identical), macaque GNAL (97% identical), rabbit GNAL (93% identical), rat Gnal (91% identical), dog GNAL (88% identical), pig GNAL (84% identical), mouse Gnal (77% identical), tropical clawed frog gnal (77% identical), guinea pig GNAL (73% identical), zebrafish gnal (67% identical), Caenorhabditis elegans gsa-1 (53% identical), Drosophila melanogaster CG30054 (32% identical), and 12 more. Paralogues in human: GNAS (62% identical), GNAI1 (35% identical), GNAI3 (35% identical), GNAO1 (35% identical), GNAI2 (35% identical), GNAT1 (35% identical), GNAT2 (34% identical), GNAT3 (34% identical), GNA14 (33% identical), GNAQ (33% identical), GNAZ (33% identical), GNA11 (33% identical), and 3 more.
Diseases named in the same sentence as GNAL in open-access papers:
GNAL is named in the same sentence as 52 diseases in open-access papers, as found by Europe PMC text mining. Sharing a sentence is not in itself a finding about the gene and the disease. The quoted sentences say what the papers report.
Dystonia (37 papers, 2013 to 2025). An abnormally increased muscular tone that causes fixed abnormal postures. "The 18p deletion syndrome encompasses GNAL and is commonly associated with dystonia, intellectual disability, dysmorphism, and short stature." (PMID 40909808, 2025). "Heterozygous loss-of-function GNAL mutations are one established cause of isolated dystonia and hyposmia." (PMID 40909808, 2025). "DYT-GNAL (dystonia 25, DYT25, OMIM#615073) is a rare form of isolated dystonia caused by pathogenic variants in GNAL, located on chromosome 18 (18p11.21)." (PMID 40724495, 2025). "At present a single case of isolated focal LD with DYT25 (GNAL) mutation has been identified, and the polygenic risk of dystonia, including LD and involving genes implicated in synaptic transmission and neural development, has been determined." (PMID 38710818, 2024). "The largest case series so far documented the response of 3 unrelated individuals with isolated dystonia due to a mutation in GNAL." (PMID 33488508, 2020). "Although this type of dystonia is rare, GNAL mutation is of interest in terms of olfaction in dystonia." (PMID 33066144, 2020). "Given the central role of Gαolf in the process, it has been proposed that dystonia-related mutations in GNAL cause the disease by disrupting its ability to relay D1R and A2R signals." (PMID 30021154, 2018). "There has been tremendous progress in understanding dystonia genetics, including the recent identification of mutations in GNAL, a gene encoding the G protein α subunit Gαolf, as the cause of DYT25, a form of isolated dystonia." (PMID 30021154, 2018). "For this, we compiled reported information about dystonia manifestations in all patients carrying mutations in GNAL that we studied." (PMID 30021154, 2018). "ANO3-related dystonia often presents with prominent tremor and involvement of the laryngeal or facial muscles, while GNAL variants more commonly cause cervical dystonia that may spread to adjacent regions." (PMID 40584247, 2025). "Although the probable cause of dystonia in patients with the 18p deletion syndrome is haploinsufficiency of GNAL, it is possible that GNAL haploinsufficiency may contribute to other neural and extra-neural manifestations." (PMID 40909808, 2025). "Our data suggests that both isoforms of GNAL are essential for normal neural function but the major isoform which encodes Gα(olf) may be more important in the pathobiology of dystonia." (PMID 40909808, 2025). "As more genetic etiologies are identified for dystonia, it has become clear that anatomic distribution relates strongly to genotype, with some genes (e.g., GNAL) typically causing a craniocervical-predominant syndrome, while craniocervical involvement is less frequent in others (e.g., TOR1A)." (PMID 37920445, 2023). "GNAL variants have been identified in less than 2% of dystonia patients of European origin." (PMID 37445923, 2023). "Other well-established genes associated with isolated dystonia include ANO3 and GNAL, both typically linked to autosomal dominant, adult-onset craniocervical or segmental dystonia." (PMID 40584247, 2025). "Currently, genes THAP1, GNAL, TOR1A, and ANO3 are linked to isolated dystonia and have undergone extensive validation." (PMID 38612382, 2024). "Previous reports suggest that GNAL variations have been detected in less than 2% of dystonia cases of European origin and contribute to disease in late adulthood." (PMID 38612382, 2024). "For example, individual AD15 has a large contiguous gene deletion containing 28 genes, but only manifested dystonia and dysarthria due to haploinsufficiency of the dystonia-related GNAL gene located in this deletion." (PMID 36781956, 2023). "With the discovery of novel dystonia genes, such as GNAL, ANO3, KCTD17, and KMT2B, these subtypes can now be allocated to the realm of inherited forms of dystonia." (PMID 33604773, 2021).
Dystonia (continued). "Only 1 case of focal adductor LD (AdLD) with DYT25 (GNAL) mutation and without any other co-occurring forms of dystonia, a family history of dystonia, or other movement disorders has been reported to date." (PMID 38710818, 2024). "In accordance with the scientific literature, we detected potentially relevant variations in known genes previously associated with CD and BSP, such as CIZ1, GNAL, and ANO3, and in other dystonia-related genes, such as KMT2B, VPS16, and KCNN2, for a total of nine patients." (PMID 37445923, 2023). "Interestingly, this downregulation was peculiar for DYT1, since the striatal levels of α‐Syn were unchanged in a different dystonia model, the GNAL (DYT25) rat model (P > 0.05)." (PMID 35420219, 2022). "DYT25 dystonia, caused by dominant mutations in GNAL, is the single inherited form of dystonia that manifests primarily (although not exclusively) during adulthood." (PMID 33616084, 2021). "Interestingly, in some patients DYT25 dystonia manifests during childhood, and GNAL participates in several of the processes affected by genes causing childhood-onset dystonia." (PMID 33616084, 2021). "Autosomal dominant mutations in the GNAL gene cause primary torsion dystonia, typically with a craniocervical onset, although progression to other sites and generalized dystonia can occur, with a phenotype resembling THAP1-associated dystonia." (PMID 33488508, 2020). "Recent advances in genetic techniques have allowed the recognition of an increasing number of genes underlying dystonia, but most of the genes discovered in the past 4 years seem to be almost exclusively found in adult-onset cases (e.g., GNAL, ANO-3) and are apparently a very rare cause of dystonia." (PMID 28066314, 2016). "Moreover, the disordered post-synaptic DARPP-32/G-protein/cAMP signaling system(s) potentially overlaps with other dystonias, particularly DYT25 caused by mutations in GNAL, suggesting that there are multiple pathways which may contribute to this phenotype." (PMID 29364887, 2018). "Thus, it is possible that mutations in GNAL and TOR1A genes may lead to dystonia via a common mechanism related to cAMP signaling." (PMID 25379658, 2014). "Sequencing of the other known PTD genes (THAP1, TUBB4a, CIZ1, ANO3, and GNAL) should be considered in patients with predominant cranial-cervical and laryngeal involvement, especially if family history is positive, with prioritization according to the age at onset and distribution of dystonia." (PMID 23596437, 2013). "The most frequently implicated genes included the well‐established isolated and combined dystonia genes VPS16 (n = 17 index patients), THAP1 (n = 14), GCH1 (n = 13), SGCE (n = 12), GNAL (n = 8), and KMT2B (n = 8)." (PMID 40533913, 2025). "The classical distinction is very hard to differentiate between isolated and combined dystonias since many genes have been shown to determine multiple dystonic presentations (e.g., ANO3, GNAL, ADCY5, and ATP1A3)." (PMID 36705216, 2022). "Additional isolated dystonia loci include DYT23 (CIZ1), DYT24 (ANO3), and DYT25 (GNAL), all of which have recently been extensively reviewed." (PMID 29110692, 2017). "We discuss the clinical implications and compare these cases with the phenotypes of dystonia-1 (DYT1); DYT6; guanine nucleotide binding protein (G protein) alpha activating polypeptide, olfactory type (GNAL); and DYT11 dystonia." (PMID 24442708, 2014). "In particular, our findings show that α‐Syn is downregulated in the striatum of mutant Tor1a+/Δgag mice but not in a distinct dystonia model, the DYT25 GNAL rat model." (PMID 35420219, 2022).
hypophysitis (9 papers, 2020 to 2025). Inflammation of the pituitary gland. "The authors identified increased pre-treatment anti-guanine nucleotide-binding protein G subunit alpha (anti-GNAL) which was associated with hypophysitis (OR = 2.66; 95% CI 1,14-7.29 p = 0.02, AUC = 0.79), and anti-CD74 levels with pneumonitis (OR = 1.25; 95% CI 1.03-1.52 p = 0.03, AUC = 0.76)." (PMID 36713389, 2022). "Some researchers have proposed a potential role for both autoantibodies as biomarkers of hypophysitis during treatment and have suggested GNAL autoantibodies as predictive biomarkers for the condition." (PMID 39941803, 2025). "In a case series involving three ICI-hypophysitis patients, there was a 1.7 and 2.5-fold increase in anti-GNAL and anti-ITM2B autoantibodies, respectively, compared to pre-treatment samples." (PMID 39247203, 2024). "The data suggested that patients who developed hypophysitis had significantly higher levels of baseline anti-GNAL compared to controls." (PMID 36672324, 2023). "Using ELISA, baseline anti-GNAL and elevation of both anti-GNAL and anti-ITM2B antibodies during treatment were shown to be associated with hypophysitis in 20 patients and anti-CD74 antibodies with pneumonitis occurrence in 32 patients with solid tumors." (PMID 33643899, 2020). "Autoantibodies against GNAL and ITM2B have been linked to the development of hypophysitis." (PMID 39941803, 2025). "This suggests that pre-existing autoantibodies against GNAL, both before and after treatment, may be linked to an increased risk of ICI-induced hypophysitis development." (PMID 39247203, 2024). "Thus, the presence of anti-GNAL antibodies before treatment can potentially be a predictive biomarker for the development of ICI-induced hypophysitis." (PMID 36672324, 2023). "Recently, the guanine nucleotide-binding protein G(olf) subunit alpha (GNAL) and the integral membrane protein 2B (ITM2B) have been identified as targets of autoantibodies in hypophysitis." (PMID 39941803, 2025). "A subsequent cohort study confirmed these findings and demonstrated the presence of anti-GNAL autoantibodies in patients prior to immunotherapy who later developed hypophysitis, compared to those who did not." (PMID 39941803, 2025). "Interestingly, the authors noted a significant rise in anti-GNAL autoantibodies in both pre- and post-treatment plasma samples compared to individuals without hypophysitis in the validation cohort." (PMID 39247203, 2024).
primary torsion dystonia (7 papers, 2013 to 2025). "Mutations in the GNAL, a gene expressed prominently in the brain, are among the main causes of primary torsion dystonia and craniocervical dystonia." (PMID 34286132, 2021). "Of our particular interest is that the GNAL gene, which encodes Gαolf, is a causative gene in primary (torsion) dystonia." (PMID 28239340, 2017). "The protein interaction models build reference to the human disease complex of hereditary spastic paraplegias (HSPs) and possibly Parkinson's disease, rather than to multiple sclerosis, in addition to primary torsion dystonia by interaction to GNAL and to severe hypotonia by GNB1." (PMID 33329738, 2020).
schizophrenia (4 papers, 2011 to 2021). A major psychotic disorder characterized by abnormalities in the perception or expression of reality. "GNAL, and possibly other genes in this region, are subject to epigenetic regulation, and constitute potential susceptibility genes for BD and schizophrenia." (PMID 21291537, 2011). "CHRNA7 downstream gene of GNAL is also considered a promising drug target for the treatment of cognitive dysfunction in schizophrenia and improves memory and executive functions in patients and healthy individuals." (PMID 33087039, 2020).
dystonia 25 (3 papers, 2023 to 2025). Autosomal dominant focal dystonia, DTY25 is a form of focal dystonia, characterized by cervical, laryngeal and hand-forearm dystonia. "Heterozygous mutations in GNAL lead to the autosomal dominant torsion Dystonia (Dystonia-25; OMIM #615073) with an onset in adulthood." (PMID 40745211, 2025). "Two illustrative examples (AD2 and AD15) both contain the GNAL gene, involved in dystonia type 25." (PMID 36781956, 2023).
generalized dystonia (3 papers, 2015 to 2025). "Homozygous GNAL mutations have been reported in siblings with generalized dystonia and intellectual disability." (PMID 40909808, 2025). "A homozygous GNAL mutation was associated with early onset generalized dystonia with mild intellectual disability in two Turkish siblings." (PMID 40909808, 2025). "Recent evidence suggests that mutations in the Gα(olf) gene (GNAL) are associated with generalized dystonia." (PMID 25860259, 2015).
glioma (2 papers, 2020 to 2024). A benign or malignant brain and spinal cord tumor that arises from glial cells (astrocytes, oligodendrocytes, ependymal cells). "By determining the prognostic values of GNAL in glioma and its association with clinicopathologic characteristics, we found that glioma patients with high GNAL expression had more significant outcomes." (PMID 38686055, 2024). "Therefore, we analyzed the types of GNAL gene alterations, including mutations, amplifications, and deep deletions, in different glioma study cohorts using cBioPortal." (PMID 38686055, 2024). "Univariate and multivariate Cox regression analyses were performed to assess the relationship between OSPRGs and the overall survival of glioma based on public cohorts, and the target gene (G Protein Subunit Alpha L, GNAL) was screened." (PMID 38686055, 2024). "In summary, immune infiltration analysis showed that GNAL was closely related to the development of an immunosuppressive microenvironment in glioma." (PMID 38686055, 2024). "To establish the relationship between 17 NOCGs and GNAL in glioma, we assessed its correlations with GNAL in CGGA325 and TCGA-GBMLGG." (PMID 38686055, 2024). "Herein, the impact of GNAL on glioma prognosis, its expressions in different clinicopathologic groups, gene mutation status, and functional enrichment were analyzed." (PMID 38686055, 2024). "The plots showed that gliomas with high GNAL expression have higher survival rates in CGGA325 and CGGA693 cohorts." (PMID 38686055, 2024). "The expression of GNAL is closely associated with clinicopathological characteristics, TIME, and the response to therapeutic interventions, highlighting its potential as a prognostic biomarker for glioma." (PMID 38686055, 2024). "Gene alterations in several oncogenes and suppressor genes were revealed in different groups of GNAL expression, suggesting that GNAL may be involved in glioma occurrence and development." (PMID 38686055, 2024). "Studies have demonstrated that the cAMP, which acts as a second signaling molecule, can inhibit the progression of glioma, and decreased expression of GNAL may be the main reason for the dysregulation of this pathway in glioma." (PMID 38686055, 2024). "A significant negative correlation was observed between all probes in LGGs and most probes in GBMs, suggesting that the low expression of GNAL in glioma may have been affected by its DNA methylation." (PMID 38686055, 2024). "Moreover, GNAL was found to be highly expressed in some glioma patients with favorable molecular biomarkers, such as IDH mutation and 1p/19q codeletion." (PMID 38686055, 2024). "Therefore, the experimental verification of the relationship between GNAL expression and immune cell expression, chemotherapy response, or immunotherapy response in gliomas is imperative." (PMID 38686055, 2024). "In conclusion, functional enrichment analysis revealed that GNAL may be involved in immunomodulatory responses in glioma." (PMID 38686055, 2024). "As for olfaction, a newly discovered risk factor for accelerating the progression of glioma, detected 17 target genes that exhibited consistent downregulation after naris occlusion; among them, ATF5 and FOSL2 were negatively correlated with GNAL." (PMID 38686055, 2024). "This implies that GNAL has the potential to be a prognostic biomarker for glioma." (PMID 38686055, 2024). "Further studies should explore whether ATF5/FOSL2 and GNAL compete or inhibit each other upstream or downstream during the development of glioma." (PMID 38686055, 2024). "Therefore, we explored the relationship between GNAL expression and its DNA methylation level in glioma." (PMID 38686055, 2024). "In summary, elevated methylation levels of GNAL may contribute to the suppression of its expression in glioma." (PMID 38686055, 2024). "Immunohistochemistry was used to evaluate GNAL level in glioma." (PMID 38686055, 2024).